TNF (tumor necrosis factor)
Diseases named in the same sentence as TNF in open-access papers (continued):
Sharing a sentence is not in itself a finding about the gene and the disease.
infection (continued). "During infection, TcpC is implicated in the control of secretion of TNF-α and IL-6 and tcpC mutants show a defect in intracellular replication in a mouse model of pyelonephritis." (PMID 23847770, 2013). "Abundance of inflammatory cytokines (TNF-α, IL-1β and IL-17) in CL supports the extensive inflammatiory nature of the disease which causes tissue damage at the site of infection." (PMID 24267152, 2013). "Type 1 and type 2 cytokines were present in the lungs of both studied groups, but at the early phase of infection only TNF-α appeared in significantly higher levels in NO-deficient mice." (PMID 23936574, 2013). "Systemic pro-inflammatory cell-mediated responses were also associated with the enhanced resolution of infection, possibly due to the synergistic effect of IFNγ, TNFα and IL-17." (PMID 23613984, 2013). "During the early stage of infection, PPARγ deficiency significantly upregulated IL-6 and TNF-α expression in malnourished mice." (PMID 23469071, 2013). "The lower fungal loads were concomitant with the high levels of pulmonary TNF-α produced by P.brasiliensis infected NO-deficient mice at the 2nd week of infection." (PMID 23936574, 2013). "Induction of a strong serum IgG and splenic cell-mediated response, dominated by pro-inflammatory cytokines IFNγ, TNFα, IL-17, was associated with the protection against infection." (PMID 23613984, 2013). "Balb/c mice are naturally resistant to P. aeruginosa and have been shown to produce higher levels of TNFα in the lung following infection while the susceptible C57Bl/6 strain produces significantly lower levels of TNFα post-infection." (PMID 23745124, 2013). "In vivo infection with S. aureus caused significantly elevated production of TNF-α and IL-6 in the livers and blood of TLR2-deficient mice compared with those in WT mice, while the hepatic and serum levels of IL-10 decreased in these mice." (PMID 24058538, 2013). "The excessive production of TNFα in pDC depleted infected mice associated with lung inflammation is in line with several studies that have shown the adverse effect of TNFα in different pathogenic conditions including infections." (PMID 24386207, 2013). "A small systematic review (9 trials) and a lager meta-analysis, both found an association between anti-TNF drug treatment and an increase in all serious infections." (PMID 24498926, 2013). "IL-1α and IL-1β double deficient mice exhibited strongly increased lung weights, an indicator of lung inflammation, 5 weeks post-infection, as did IL-1R1 deficient mice and TNF KO mice which succumbed at 4 weeks." (PMID 25400917, 2013). "We found that macrophages were implicated in TNF-α production in the acute phase of infection since an increased percentage (∼13%) of TNF-α+F4/80+CD11b+ population was observed in spleen from infected mice." (PMID 23650544, 2013). "In earlier lactations, allele A of the gene encoding TNF-α, whose role is to activate the immune system during infection, proved to be very beneficial – it is linked to higher immunity against infection compared with the other allele in this locus." (PMID 23758855, 2013). "Lung IFNγ levels were highly elevated in mice deficient for both IL-1α and IL-1β or for IL-1R1 at 5 weeks after M. tuberculosis infection, reminiscent of TNF deficient mice at 4 weeks, when they succumb to infection." (PMID 25400917, 2013). "In relation to existing research, our findings differ from earlier studies that reported an association between anti-TNF drug treatment and an increase in all serious infections in RA patients." (PMID 24498926, 2013). "Conversely, TNF-α was associated significantly with groups having active infection (CP Ag+ and INF) indicating a possible association with filarial infection rather than pathology alone." (PMID 22685406, 2012).
infection (continued). "This would be consistent with the known increased risk of acquiring MTB-complex infection due to impairment of cell-mediated immunity induced by therapy with corticosteroids or with anti-TNFα therapy." (PMID 23216965, 2012). "TNF-α is one of the first cytokines to be released by macrophages in response to infection and, once in the circulation, it causes systemic inflammation through stimulating the widespread release of downstream cytokines, such as interleukin-6 (IL-6) and IL-8." (PMID 22340283, 2012). "T. cruzi-infected mice are highly susceptible to systemic inflammation, which can be caused by infection itself in mice lineages that develop severe inflammatory response or by administration of TNF, anti-CD3, SEB, or LPS." (PMID 22496958, 2012). "Based on our studies, this loss of NEMO during infection would be predicted to leave infected cells vulnerable to the induction of programmed necrosis by TNF." (PMID 22848449, 2012). "It causes prominent edema at the site of infection, the inhibition of neutrophil function, and suppression of the production of TNFα and IL-6 by monocytes." (PMID 22291977, 2012). "Here, we demonstrated that macrophages from NOD1-, NOD2-, and Rip2-deficient mice produced lower levels of TNF-α following infection with live Brucella abortus compared to wild-type mice." (PMID 22203860, 2012). "Taken together, these results demonstrate that production of IFN-γ and TNF are dysregulated in the lungs of NFATp-deficient mice following MTb infection, particularly within the first six weeks." (PMID 22844476, 2012). "TNF and Nos2 expression appear to be critical for limiting Salmonella growth in mice, as evidenced by the marked susceptibility of p40−/− mice to infection." (PMID 22624013, 2012). "Infection of H. pylori also disrupts gastric homeostasis and induces multiple inflammatory cytokine production within local mucosal, components such as IL-1β, TNF-α, and IL-10 genotypes are associated with increased risk for developing gastric cancer." (PMID 23217022, 2012). "A recent systematic review assessing the risk of orthopaedic surgical site infection in patients with RA taking anti-TNF agents concluded that there was insufficient data internationally to reach any conclusion." (PMID 23251815, 2012). "In experimentally BDV-infected mice and rats, an up-regulation of native TNF in the brain is regularly observed, even very early after infection which underlines the essential role of TNF for the following inflammatory events also in our mouse model." (PMID 22848506, 2012). "TNF is an important cytokine involved in initiating the protective immune response; therefore, patients receiving this therapy are at a high risk of infection." (PMID 22405136, 2012). "The TNF polymorphisms studied were associated with risk of infection by influenza A/H1N1 virus during the pandemic in Mexico in 2009." (PMID 23148654, 2012). "Induction of increased levels of TNF-α to macrophage cultures resulted in resistance to subsequent infection with L. pneumophila serotype 1; however, susceptibility was restored with addition of TNF-α antibodies to the culture." (PMID 23092579, 2012). "It is interesting to note that the msrA mutant strain of M. genitalium is deficient in inducing the proinflammatory cytokine TNF-α, the principal mediator of inflammatory response to infection." (PMID 22558404, 2012). "A larger retrospective study of 128 patients undergoing major orthopaedic surgery revealed an increased infection risk in those who remained on TNFα antagonists (odds ratio 21.8), and an associated increased risk of deep vein thrombosis (odds ratio 2.8)." (PMID 22697352, 2012). "Infection of MΦ and DCs with live mycobacteria is generally associated with induction of a strong pro-inflammatory phenotype with production of TNF, IL-12 and IL-6 that in turn is accompanied by the regulatory response, including secretion of IL-10." (PMID 22880012, 2012).
infection (continued). "A previous study demonstrated that TNF-α gene polymorphisms and high expression of this cytokine were associated with human infection with T. cruzi." (PMID 22811738, 2012). "At 3 days post-infection, NF-κB was implicated in transcriptional upregulation in addition to IRFs 1 and 2, possibly due to the increased levels of TNF-α observed at this time." (PMID 22713837, 2012). "Most recent studies suggest that anti-TNF-α agents are associated with a slight increased risk of serious infections, especially in the early phase of treatment and an absolute rate of infections relatively low." (PMID 22645622, 2012). "In experimental infection with Theiler virus, TNF, IL-6 and associated inflammatory changes mainly contribute to the occurrence of acute seizures." (PMID 22848506, 2012). "Because germinal center reactions are critical for optimal antibody induction, we postulate that TNF blockade alters the effector and memory B cell responses, contributing to increased risk of infection and poor response to vaccination." (PMID 22177419, 2011). "Studies on humans have associated TNF-alpha with phenomena of tissue injury during the chronic phase of infection." (PMID 21408088, 2011). "Neutralization of either TNF-α or γδ T cells from wt mice enhanced susceptibility to B. abortus colonization one week after infection." (PMID 21765931, 2011). "Klebsiella-infected TCRδ−/− mice are found to have decreased levels of IFN-γ and TNF-α, which has been postulated to result in enhanced susceptibility to infection." (PMID 21765931, 2011). "In conclusion, the present results suggest that the TNF-238A allele exerts a significant effect on human susceptibility to infection." (PMID 21408088, 2011). "An additional study investigating the cause of TE in mice revealed that TNFα transcripts were elevated after infection in the brain." (PMID 21687650, 2011). "Presence of mutation in TNF-α gene can influence the effectiveness, performance and capability of immune responses against this infection." (PMID 22737473, 2011). "We expected a weaker ability since activation of TLR2-deficient BMDC upon infection with the bacterium in vitro was impaired as analyzed by IL-12p40 and TNF secretion and induction of NF-κB." (PMID 22096480, 2011). "Although TLR2-deficient BMDC were impaired to secrete TNF and IL-12p40 upon infection with C. pneumoniae in vitro, both factors were presumably not required for T-cell stimulation." (PMID 22096480, 2011). "The implications of this finding should be considered in the context of the increased susceptibility to infections observed in anti-TNF treated patients and suggest the need for vaccines with enhanced immunogenicity for these patient populations." (PMID 22177419, 2011). "TNF-α and HLA polymorphisms, which are risk factors for infection, substantially influence the risk of AD as well." (PMID 21816039, 2011). "It is known that preventing TNF-α activity can increase host susceptibility to infection, and thus it will be important to determine the role of leukocyte ADAM17 in pulmonary defense against bacterial infection." (PMID 21603616, 2011). "Following infection of murine bone-marrow-derived macrophages we found the mutated strain induced similar levels of TNF-α as the wild-type and complemented strains." (PMID 21931620, 2011). "Infection with M. tuberculosis is associated with an active inflammatory immune response, characterized by elevated expression of both TNF-α and IFN-γ." (PMID 21253484, 2011). "Most of the available data on the infection risk of targeted therapies concern inhibitors of tumor necrosis factor alpha (TNF-α), which have been in clinical use the longest, while information on the newer biologicals is much more limited." (PMID 22081766, 2011). "The disease-related infection risk and the infection risk associated with the use of TNF-α inhibitors (infliximab, adalimumab, etanercept, golimumab and certolizumab pegol), rituximab, abatacept and tocilizumab are discussed." (PMID 22081766, 2011).
infection (continued). "The alteration of barrier function after PMN transmigration following infection with S. suis or by TNFα stimulation was associated with an altered actin cytoskeleton and TJ morphology." (PMID 21592385, 2011). "Definitively, the transcription of IFN-γ and TNF-α genes was rapidly enhanced post-MHV-3 infection in PD-1-deficient mice, as compared to WT controls." (PMID 21750671, 2011). "The present results suggest that the polymorphism at position -238 influences susceptibility to infection and that this allele is associated with higher TNF-alpha production in seropositive individuals." (PMID 21408088, 2011). "A Swedish observational study reported an increased relative risk for hospitalisation due to infection during the first year of anti-TNF treatment, which subsided with increasing duration of treatment." (PMID 22081766, 2011). "TNF-α and the encoding gene impact development of CC by increasing susceptibility to infection with HR-HPV." (PMID 21119665, 2011). "The objectives of the present study were to evaluate the microbial agents, natural history and risk factors of TJA infections in patients receiving TNFα blockers, through a case-control study." (PMID 20637100, 2010). "Previous analyses have suggested that secretion of TNFα is unaffected or even decreased during macrophage infection with wild type compared to Esx-1-deficient mycobacteria." (PMID 20463815, 2010). "The inhibition of IL-1β and TNF-α is a critical step in the pathogenesis of infection because mice deficient in these molecules are partially sensitive to infection with the yopH mutant." (PMID 20565713, 2010). "Actually, the herein reported case-control study was designed to assess risk factors of TJA infection in patients exposed to TNFα blockers." (PMID 20637100, 2010). "Mice deficient in TNF-alpha are more susceptible to CO92 delta yopH infection with 40% of the mice succumbing to infection." (PMID 20565713, 2010). "The mechanisms responsible for the inherent relative resistance of macrophages to infection by T. cruzi appear to be linked to the production of the inflammatory cytokines TNF-α, IL-12p70, and IFN-γ which drive nitric oxide production." (PMID 20169081, 2010). "TNF-α haplotype analyses indicated that there was a significant association between carriage of the haplotype 3 and the risk of infection (p = 0.04)." (PMID 20420684, 2010). "As anti tumor necrosis factor agents are frequently associated with infection, including tuberculous infection, this case highlights the need for a high index of suspicion for other severe bacterial infections in patients on immunosuppressants." (PMID 21083879, 2010). "In humans, the binding of TLR-4 initiates a host inflammatory response involving cytokines such as IL-1 and TNF, thus playing a critical role in the pathogenesis of infection-associated PTB." (PMID 20706662, 2010). "On the other hand, the production of TNF and NO contributes to infection-associated pathogenicity including liver cell apoptosis/necrosis, resulting in organ failure and thus negatively affecting survival of the T. brucei infected host." (PMID 20714353, 2010). "TNF-alpha restricts the growth of Mtb in alveolar macrophages, and the multiplication of virulent Mtb in monocyte-derived macrophages (MDMO) is associated with suppression of TNF-α production during the early periods after infection." (PMID 19649276, 2009). "The R form lacks a surface polyketide compound, glycopeptidolipid (GPL), and causes more severe infections in mice, strongly inducing TNF secretion by macrophages." (PMID 19543527, 2009). "Our results confirmed that infection with Leishmania caused a significant inhibition of LPS-mediated expression of IL-12, TNF production, and NO generation in MØs." (PMID 19104650, 2008). "While 100% of mice with complete TNF deficiency (TNF−/−) succumbed to infection, 50% of TNFtm/tm mice were able to control M. bovis BCG infection and survived the experimental period." (PMID 18544042, 2008).
infection (continued). "We next characterized brain-sequestered leukocytes, in wild-type and TNF deficient mice with severe neurological symptoms after PbA infection and in LTβR or LTβ deficient mice at the same day after infection." (PMID 18612394, 2008). "Within 3–4 weeks of infection TNF−/− mice displayed rapid weight loss, impeded locomotor activity and succumbed to infection between 5 and 8 weeks." (PMID 18544042, 2008). "In a macrophage model of infection the changes in cell surface structures in hVISA/VISA strains were associated with significantly reduced NF-κB activation resulting in reduced TNF-α and IL-1β expression." (PMID 18304359, 2008). "The rapid activation of tissue macrophages early in the innate immune response to infection causes the release of cytokines interleukin-6 (IL-6), interleukin-1β (IL-1β), and tumor necrosis factor-α (TNF-α), along with other proinflammatory mediators." (PMID 18242584, 2008). "While wild-type C57BL/6 and TNF-deficient mice presented signs of ischemic brain damage and vascular blood flow perturbations upon blood stage PbA infection, LTαβ and LTβR deficient mice displayed a normal MRI." (PMID 18612394, 2008). "A predominant Th1 immune response was observed during infection, as 6 of 11 investigated Th1 associated genes, including TNF, IFNG, and some IFNG-signaling responsive genes (SOCS1, STAT1, WARS and IRF1), were strongly up-regulated at 24 hpi and/or 48 hpi." (PMID 18811943, 2008). "We compared the risk of serious infection in 8,659 patients treated with anti-TNFα with that in 2,170 patients treated with traditional disease-modifying antirheumatic drugs (DMARDs) recruited to the British Society for Rheumatology Biologics Register." (PMID 17763441, 2007). "This is particularly important if anti-TNF treatments are implemented in regions of the world where infection risk is elevated." (PMID 17953477, 2007). "The risk of infection attributable to anti-TNFα therapy measured in an observational study cannot be adequately summarized as a single estimate." (PMID 17763441, 2007). "The adjusted incidence rate ratios for the 3 anti-TNFα drugs compared with the DMARD cohort showed an ∼4-fold or greater risk of serious infection in the first 90 days." (PMID 17763441, 2007). "It would be expected that any effect that anti-TNFα drugs have on susceptibility to infection would subside within months of discontinuing the drug." (PMID 17763441, 2007). "The influence of these selection variables on serious infection during the lag window makes it very difficult to explore the true pattern of infection risk for the anti-TNFα drugs once discontinued." (PMID 17763441, 2007). "We used a large national observational study to assess the impact of the various issues addressed above on the estimated risk of infection following anti-TNFα therapy in patients with RA." (PMID 17763441, 2007). "Similarly, infection of Iba1+ macrophages within alveoli and associated expression of TNF-α and ISG proteins has been reported in dogs naturally infected with CDV." (PMID 41405202, 2026). "Finally, we found that lasR LOF mutations altered the inflammatory profile upon infection of CF macrophages, with a shift from IL-1 family cytokine expression toward canonical inflammatory markers, including IL-6 and TNFα." (PMID 41925330, 2026). "Despite secreting substantial amounts of Interleukin-17 (IL-17) and TNF-α, these cells show a significant reduction in cytotoxic function, which may lead to an increased risk of infection and carcinogenesis." (PMID 41495287, 2026). "However, non-TNF agents with lower infection risk, such as apremilast, IL-17 or IL-23 inhibitors, or abatacept, are advised." (PMID 41362871, 2026). "Interestingly, WT-infectedmice displayed a decrease in TNF compared to their naive counterparts.In contrast, infection was associated with increased levels of IFN-γand MHC-II expression across both MO subsets." (PMID 41365681, 2026).